RANBP3 (RAN binding protein 3)
Description:
Acts as a cofactor for XPO1/CRM1-mediated nuclear export, perhaps as export complex scaffolding protein. Bound to XPO1/CRM1, stabilizes the XPO1/CRM1-cargo interaction. In the absence of Ran-bound GTP prevents binding of XPO1/CRM1 to the nuclear pore complex. Binds to CHC1/RCC1 and increases the guanine nucleotide exchange activity of CHC1/RCC1. Recruits XPO1/CRM1 to CHC1/RCC1 in a Ran-dependent manner. Negative regulator of TGF-beta signaling through interaction with the R-SMAD proteins, SMAD2 and SMAD3, and mediating their nuclear export.
Tractability: PROTAC: ubiquitination databases record sites on it; its protein half-life has been measured.
Gene: Protein-coding gene on chromosome 19 (5,916,139 to 5,978,144, reverse strand). Ensembl gene ENSG00000031823.
Subcellular location: Cytoplasm; Nucleus
Subcellular location (Human Protein Atlas): Nucleoplasm
Gene Ontology:
Molecular function: protein binding; R-SMAD binding
Biological process: protein export from nucleus
Cellular component: cytoplasm; nucleoplasm; nucleus; nuclear pore
Genetic constraint (gnomAD): Loss-of-function variants: 14 observed, 77.92 expected, observed/expected ratio (o/e) 0.18, 90% interval 0.12 to 0.28. The upper end of that interval is the gene's LOEUF score, 0.28, which puts it in group 1 of 6, group 1 being the genes least tolerant of losing a copy. Missense variants: 586 observed, 776.11 expected, observed/expected ratio (o/e) 0.76, 90% interval 0.7 to 0.81. Synonymous variants: 315 observed, 320.4 expected, observed/expected ratio (o/e) 0.98, 90% interval 0.9 to 1.08.
Homologues: Orthologues: macaque RANBP3 (98% identical), chimpanzee RANBP3 (96% identical), dog RANBP3 (90% identical), pig RANBP3 (88% identical), guinea pig RANBP3 (85% identical), rabbit RANBP3 (84% identical), mouse Ranbp3 (79% identical), rat Ranbp3 (78% identical), tropical clawed frog ranbp3 (64% identical), zebrafish ranbp3b (58% identical). Paralogues in human: RANBP2 (29% identical), RANBP3L (29% identical), RGPD4 (22% identical), RGPD3 (21% identical), RGPD1 (21% identical), RGPD2 (21% identical), RGPD5 (21% identical), RGPD6 (21% identical), RGPD8 (21% identical), RANBP1 (8% identical).
Diseases named in the same sentence as RANBP3 in open-access papers:
RANBP3 is named in the same sentence as 10 diseases in open-access papers, as found by Europe PMC text mining. Sharing a sentence is not in itself a finding about the gene and the disease. The quoted sentences say what the papers report.
melanoma (3 papers, 2021 to 2026). A malignant, usually aggressive tumor composed of atypical, neoplastic melanocytes. "Ran-binding protein 3 (RANBP3) regulates melanoma cell proliferation and also acts as a cofactor for chromosome region maintenance 1 (CRM1)-mediated nuclear export." (PMID 41601480, 2026). "Recently, RanBP3 has been reported as a potential regulator in melanoma biology, hepatocellular carcinoma, prostate cancer, and ovarian cancer." (PMID 34504783, 2021). "RANBP3 regulates melanoma cell proliferation and ß-Catenin import in colorectal cancer." (PMID 37019990, 2023).
colon cancer (2 papers, 2006 to 2022). "Selection of some of the most suitable mRNAs (TMEM69, RANBP3 and PRSS22) that were assayed in blood samples from normal subjects and patients with colon cancer as possible markers for the presence of epithelial cells in the blood, using reverse transcription – polymerase chain reaction (RT-PCR)." (PMID 17054783, 2006).
influenza (2 papers, 2014 to 2024). An acute viral infection of the respiratory tract, occurring in isolated cases, in epidemics, or in pandemics; it is caused by serologically different strains of viruses (influenzaviruses) designated A, B, and C, has a 3-day incubation period, and usually lasts for 3 to 10 days. "Therefore, RanBP3 could be another cellular target protein for blocking virus replication and possibly treating influenza." (PMID 24672735, 2014). "This includes the cellular NF-κB pathway, which is essential for influenza viral RNA synthesis and the CRM1/RanBP3 nuclear export pathway, which facilitates the transport of viral RNP complexes from the nucleus to the cytoplasm of the infected cell." (PMID 24672735, 2014).
leukaemia (2 papers, 2021 to 2024). "Consistently, the protein and mRNA detection showed that the RanBP3 levels in CML cells (BCR-ABL+) were much higher than that of other leukemia cells (BCR-ABL-)." (PMID 34504783, 2021).
breast carcinoma (1 paper, 2024). "Therefore, it can be concluded that the methylationlevel of the RANBP3 gene is related to HRexpression in breast cancer, and the methylation levelof the LCP2 gene is associated with the degree oftumour malignancy." (PMID 39139156, 2024). "When the methylation levels of RANBP3 are reduced, we will be alert to the occurrenceof HR+ breast cancer." (PMID 39139156, 2024). "Specifically, theobserved lower methylation level of the RANBP3gene in HR+ breast cancer compared to HR- breastcancer prompts an exploration of the relationshipbetween RANBP3 gene methylation levels and triplenegativebreast cancer." (PMID 39139156, 2024). "Notably, RANBP3 showed a tendency towards lower methylation in HR+ breast cancer, and LCP2 methylation was correlated with tumour malignancy." (PMID 39139156, 2024). "Our findings propose that the genes RANBP3, LCP2, and GRAP2, located at the identified methylation sites, hold significant potential as molecular markers in blood for the supplementary diagnosis of breast cancer." (PMID 39139156, 2024). "Subsequently, we investigated the methylation status of the genes Ran-binding protein 3 (RANBP3), Lymphocyte cytoplasmic protein 2 (LCP2), and GRB2 related adaptor protein 2 (GRAP2), situated at the specified sites, using cancer and canceradjacent tissues from 17 breast cancer patients." (PMID 39139156, 2024). "Interestingly, the methylation level of the RANBP3 gene in cancer tissues of theHR+/HER2- and HR+/HER2+ types was significantlylower than that in the HR-/HER2+ type(P=0.000, P=0.007), suggesting a correlationbetween the methylation level of the RANBP3 geneand HR expression in breast cancer." (PMID 39139156, 2024).
chronic myeloid leukemia (1 paper, 2021). "But the potential role of the CRM1 cofactor RanBP3 (Ran Binding Protein 3) is left unrevealed in chronic myeloid leukemia (CML)." (PMID 34504783, 2021).
Infertility (1 paper, 2022). "Unfortunately, it is not known if RANBP3 depletion results in a loss of fertility although one study has found an association between decreased RANBP3 expression and human infertility." (PMID 35133275, 2022).
tumor (5 papers, 2011 to 2024). "The results show that RanBP3 is a tumor suppressor in CRC and is associated with patient survival." (PMID 36270974, 2022). "Furthermore, the tumor xenografts established by RanBP3‐deficient DLD1‐sgRanBP3 and HCT15‐sgRanBP3 cells were significantly larger than those established by the control cells, with decreases in size of 62.8% and 66.2%, respectively." (PMID 36270974, 2022). "As the mislocalization of cancer-related proteins and tumor suppressor molecules may be the indispensable cause of tumorigenesis, further study will be performed to figure out the possible effects of RanBP3-medidated nuclear export in other cancers." (PMID 34504783, 2021). "High RanBP3 expression was detected in 42.0% (42/100) of tumor tissues and 64.8% (47/73) of normal tissues." (PMID 36270974, 2022). "In short, these data collectively suggest that RanBP3 is a tumor suppressor and favorable prognostic biomarker in CRC." (PMID 36270974, 2022). "Ki‐67 immunostaining also showed that knockout of RanBP3 promoted the proliferation index of CRC tumor xenografts." (PMID 36270974, 2022). "Similarly, the inhibitory effects of NU2058 on the β‐catenin pathway and Ki‐67 proliferation index in CRC tumor xenografts were markedly attenuated by RanBP3 knockout." (PMID 36270974, 2022). "And other studies have begun to concern about the potential role of RanBP3 in tumor progression." (PMID 34504783, 2021). "Both CM presented proteins involved in proliferation of both tumor and non-tumor cells, of which CAPN1, CST1, LAMC2 and RANBP3 stood out in CM3D and GPC6, ILK, MAPK1, MIF and PICALM in CM2D." (PMID 34884877, 2021). "Considering the outstanding anti-tumor effect of silencing RanBP3 in both imatinib sensitive and resistant CML cells, it is necessary to investigate the relationship between RanBP3 and imatinib sensitivity in these cells." (PMID 34504783, 2021).
cancer (3 papers, 2021 to 2024). A tumor composed of atypical neoplastic, often pleomorphic cells that invade other tissues. "Here, we provide the first evidence suggesting that RanBP3 expression is downregulated in cancer tissues and can predict poor prognosis in CRC patients." (PMID 36270974, 2022). "Considering the important role of RanBP3 in CRM1-medidated nuclear export, it is urgent to determine the effect of RanBP3 on cancer." (PMID 34504783, 2021). "Our analysis revealed that RANBP3, LCP2, and GRAP2 genes exhibited significant methylation differences between cancer and cancer-adjacent tissues." (PMID 39139156, 2024). "In conclusion, we proved that RanBP3 was important in regulating proliferation and apoptosis in CML, and the potential mechanism was changing the distribution of cancer-related proteins between the cytoplasm and nucleus." (PMID 34504783, 2021). "A ROC curve showed that when the sensitivitywas 86.67% (RANBP3), 82.35% (LCP2) and88.24% (GRAP2), the specificity of breast cancerdiagnosis was 93.3%; the sensitivity of identifyingbreast cancer patients by the comprehensive methylationlevel of the three genes was 94.1%, with aspecificity of 93.3%." (PMID 39139156, 2024). "Ran‐binding protein 3 (RanBP3) may be a promising prognostic biomarker and therapeutic target in CRC, and a preclinical rationale is provided for NU2058 as a potential strategy for cancer treatment." (PMID 36270974, 2022).
RANBP3 also shares sentences with these, for which no sentence is quoted: colorectal cancer (1 paper).